AMH (anti-Mullerian hormone)
Diseases named in the same sentence as AMH in open-access papers (continued):
Sharing a sentence is not in itself a finding about the gene and the disease.
hyperandrogenism (continued). "Follicular resistance to FSH signaling in PCOS may be intrinsic to the disease, secondary to intra-ovarian hyperandrogenism, and consequent to elevated levels of anti-Mullerian hormone (AMH) secreted by the growing cohort of preantral follicles." (PMID 40869727, 2025). "Elevated serum AMH in women with hyperandrogenism or oligocystic ovarian syndrome may indicate to a clinician the presence of PCOS in the absence of a reliable ultrasound." (PMID 40281834, 2025). "It is therefore possible that AMH‐induced LH hypersecretion contributes to hyperandrogenism and may stimulate further AMH secretion, inducing a positive feedback loop between androgens, AMH, and GnRH/LH." (PMID 40251138, 2025). "In addition, hormonal disturbances included increases in LH and AMH levels, as well as hyperandrogenism." (PMID 38408933, 2024). "In line with our previous studies, PCOS animals showed excess body weight gain/ovarian mass, abnormal metabolic indices (fasting insulin, blood glucose and HOMA-IR), androgen excess, multiple ovarian cysts, elevated AMH and leptin and decreased SHBG, adiponectin and 17-β estradiol." (PMID 38561673, 2024). "Various factors lead to hyperandrogenism in PCOS, which in turn causes higher serum AMH." (PMID 36900051, 2023). "However, there remains limited support for AMH as a replacement for oligo/amenorrhea or hyperandrogenism." (PMID 36900051, 2023). "Given its utility as a marker of PCOS, serum AMH may be considered as an alternative to hyperandrogenism." (PMID 36900051, 2023). "Thus, a diagnosis of PCOS was based on having two of three features of either oligo/amenorrhea, hyperandrogenism, or AMH above a cut-off threshold." (PMID 36900051, 2023). "Overeating disorders and obesity may affect oogenesis due to epigenetic modifications of the hypothalamic-pituitary-gonadal (HPG) axis and increased levels of anti-Mullerian hormone (AMH), which inhibits aromatase, leading to hyperandrogenism." (PMID 37513562, 2023). "However, others have found that a higher cut-off of AMH was necessary when used as a substitute for hyperandrogenism in criteria for PCOS." (PMID 36900051, 2023). "According to this hypothesis, in a PCOS cohort, Rosenfield and Ehrmann found that plasma AMH concentration was independently associated with the presence of PCOM and intraovarian hyperandrogenism." (PMID 35701786, 2022). "In addition, the authors showed that if AMH cannot cross the placental barrier, AMH treatment decreased Cyp19a1 expression in the placenta, which likely induces in utero hyperandrogenism." (PMID 36289767, 2022). "The increase in serum AMH in women with hyperandrogenism and/or oligoovulation may indicate the presence of PCOS." (PMID 35698127, 2022). "Alternatively, hyperandrogenic PCOS mothers with elevated serum AMH levels in pregnancy may have reduced placental aromatase expression, providing a potential maternal androgen contribution to female fetal hyperandrogenism." (PMID 35012577, 2022). "Simultaneously, hyperandrogenism may increase AMH levels through its proposed disruptive effects on follicular development." (PMID 34277990, 2021). "This could mean that the AMH excess is the hallmark of a GCs deregulation that plays a major role in the anovulation of PCOS, besides other contributors such as hyperandrogenism and/or excessive LH secretion and/or hyperinsulinism." (PMID 33013710, 2020). "Elevated levels of anti-Mullerian hormone might have a synergistic relationship with hyperandrogenism; evidence from rodent models indicates that excess prenatal exposure to AMH or androgens can result in PCOS-like phenotypes." (PMID 31367382, 2019). "By a principal component analysis, it has been shown a high serum AMH level can be considered as a marker of hyperandrogenism and could also be used as a substitute for this item in the Rotterdam classification." (PMID 26691645, 2015).
hyperandrogenism (continued). "A simple linear regression analysis was performed to establish the relationship between AMH in the follicular fluid and the systemic response to the treatment, which included ΔT and ΔHOMA as indicators for improved hyperandrogenism and insulin resistance, respectively, and serum ΔAMH." (PMID 20663178, 2010). "Additionally, the relationship between AMH and testosterone and other biochemical markers of hyperandrogenism remains unclear based on current evidence." (PMID 36900051, 2023). "In this review, we discussed the studies that investigated the sensitivity and specificity of AMH both as a predictor for PCOS and as an alternative to each of Rotterdam’s diagnostic criteria: polycystic ovarian morphology on ultrasound, oligo/amenorrhea, and hyperandrogenism." (PMID 36900051, 2023). "Therefore, AMH mutations in PCOS are suggested to result in decreased AMH-mediated inhibition of CYP17 expression and androgen biosynthesis, leading to syndrome-specific hyperandrogenism." (PMID 33746952, 2021). "Thus, the number of small antral follicles increases, when the level of AMH increases, which leads to fewer mature antral follicles, failure to provide the necessary substrates for estrogen generation, and furthermore, to hyperandrogenism (such as high testosterone, DHEA) and ovarian dysfunction." (PMID 32703275, 2020). "Women with PCOS are noted to have higher levels of AMH and increased levels of serum AMH correlate highly with PCOS, polycystic ovarian morphology, hyperandrogenism, and oligo/amenorrhea." (PMID 37361535, 2023). "Increased levels of serum AMH correlate highly with PCOS, polycystic ovarian morphology, hyperandrogenism, and oligo/amenorrhea." (PMID 36900051, 2023). "AMH acts on the ovary by inhibiting FSH-induced aromatase activity, which contributes to hyperandrogenism, and by inhibiting antral follicle growth contributing to the polycystic ovarian morphology (PCOM)." (PMID 36309748, 2022). "The search terms used were: “AMH”, “PCOS”, “Hyperandrogenism”, “AMH assay”, “ovarian reserve”, “AMH in PCOS”, “AMH in diagnosis and treatment of PCOS” The resulting references, including reviews, were used as leads for further literature searches." (PMID 34830389, 2021). "Serum AMH concentration is higher in women with PCOS than in healthy women, which is related to severity of hyperandrogenism and oligo-anovulation." (PMID 34790167, 2021). "AMH levels are higher in anovulatory compared to ovulatory women with PCOS and also positively predict symptom severity, including hyperandrogenism and polycystic ovarian morphology." (PMID 34295358, 2021). "The increased AMH levels in their cases correlate with the severity of PCOS manifestations (amenorrhea and hyperandrogenism)." (PMID 32481491, 2020). "In addition, obesity might be correlated with high serum levels of AMH and hyperandrogenism." (PMID 31980027, 2020). "Serum AMH was higher in patients with more features consistent with PCOS (menstrual disturbance, hyperandrogenism, PCOM by Rotterdam criteria)." (PMID 31616381, 2019). "Serum AMH was higher in women with all three cardinal features of PCOS (menstrual disturbance, hyperandrogenism, polycystic ovarian morphology) when compared to women with none of these features (65.6 vs. 14.6 pmol/L; P < 0.0001)." (PMID 31616381, 2019). "Serum AMH level is also correlated to the severity of PCOS symptoms and is higher when hyperandrogenism or oligo-anovulation is present." (PMID 26691645, 2015). "This leads to the conclusion that the mechanism of excessive AMH production is related to hyperandrogenism, although it is not fully explained." (PMID 40564059, 2025). "Remarkably, in the case of menstrual irregularity and hyperandrogenism, ultrasound or AMH confirmation is not obligatory." (PMID 41556019, 2025).
hyperandrogenism (continued). "In addition to insulin, the anti-mullerian hormone (AMH), which is typically elevated in PCOS, also stimulates gonadotropin hormone-releasing hormone (GnRH) neurons, potentially promoting hyperandrogenism." (PMID 40650016, 2025). "In cases where irregular menstrual cycles and hyperandrogenism are evident, ultrasound or AMH testing is not necessary for diagnosis." (PMID 39273337, 2024). "In adolescents, both hyperandrogenism and ovulatory dysfunction must be present for diagnosis, as ultrasound and AMH testing lack specificity and are therefore not recommended." (PMID 39273337, 2024). "While AMH could be evaluated as a potential replacement for hyperandrogenism in PCOS criteria, the benefit of this is unclear given a higher threshold value for AMH is necessary to allow for diagnosis." (PMID 36900051, 2023). "In a study of 211 Caucasian women, a threshold of 45 pmol/L (6.3 ng/mL) but not 29 pmol/L (4.1 ng/mL) for AMH substituted for hyperandrogenism resulted in effective diagnosis of PCOS." (PMID 36900051, 2023). "One hypothesis proposed is that hyperandrogenism in PCOS hypersensitizes granulosa cells to FSH, resulting in excessive preantral follicular growth and AMH expression, which in turn inhibits FSH-induced aromatase expression." (PMID 36900051, 2023). "From these analyses, it can be assumed that the impact of insulin resistance (HOMA-IR) and hyperandrogenism (FAI) on the increase in the LH/FSH ratio in lean PCOS patients occurs through the elevation of AMH levels as an intermediary variable rather than through direct effects." (PMID 38589425, 2024). "The average AMH in women with PCOS with all three features of Rotterdam criteria has been shown to be higher than those with only features of oligo/amenorrhea and PCOM (without hyperandrogenism), suggesting that serum AMH correlates strongly with hyperandrogenism." (PMID 36900051, 2023). "Furthermore, AMH was significantly higher in lean women with PCOS who had hyperandrogenism than in those without." (PMID 36733795, 2022). "Anti-Müllerian hormone (AMH) correlates with the severity of the PCOS phenotype, with the highest AMH serum levels found in women with the classical PCOS phenotype A, characterized by PCO-like morphology of the ovaries, ovulatory dysfunction, and hyperandrogenism." (PMID 34218388, 2021). "Therefore, the declined AMH levels might not only account for the reduced follicle excess of PCOM, but also line up with the elevated ovulation rate and ameliorative hyperandrogenism, thus improving the fertility outcomes." (PMID 34790167, 2021). "Importantly, irregular menstrual cycles and hyperandrogenism alone may suffice for diagnosis without imaging in adults, while AMH can be considered an alternative to ultrasound when appropriate." (PMID 41583231, 2025). "Based on the main difference in androgen levels, we hypothesized that MALAT1 expression in GCs might be downregulated in women with PCOS with hyperandrogenism, while MALAT1 level might be up-regulated in patients without hyperandrogenism and with high AMH." (PMID 35573984, 2022). "AMH levels alone may not be able to be used as criteria for adolescent PCOS diagnosis but might help supporting the diagnosis if adolescents meet both irregular menstrual cycles and hyperandrogenism criteria." (PMID 36010282, 2022).
Insulin resistance (59 papers, 2010 to 2026). Increased resistance towards insulin, that is, diminished effectiveness of insulin in reducing blood glucose levels. "A high absolute RC value (e.g., > 0.4) indicates a strong association between a marker (e.g., AMH) and a factor (e.g., insulin resistance)." (PMID 41220482, 2025). "Previous research has also suggested that lower AMH concentrations in men are associated with conditions that increase the risk of type 2 DM, including metabolic syndrome and insulin resistance." (PMID 36471299, 2022). "Weight loss improves all features of the disease, via decreased insulin resistance and lower androgen levels, leading to improvement in ovarian function and lower AMH." (PMID 36309748, 2022). "By decreasing insulin resistance, metformin may help normalize AMH levels by reducing the number of small antral follicles that are typically associated with elevated AMH." (PMID 40281834, 2025). "Obesity, high AMH, and insulin resistance (IR) are shown to be strongly associated with PCOS." (PMID 34336524, 2021). "Conversely, our patient shows a clear coexistence of hyperandrogenic PCOS phenotype A and subsequently developed hypogonadotropic hypogonadism, retaining significantly elevated AMH levels and pronounced insulin resistance." (PMID 41515619, 2026). "Previously, we reported that in women with PCOS, AMH is increased and correlates with androgen levels, ovarian size, and insulin resistance." (PMID 40868196, 2025). "Key markers, including luteinizing hormone (LH), anti-Müllerian hormone (AMH), insulin, and Homeostatic Model Assessment for Insulin Resistance (HOMA-IR), reflect disruptions in the hypothalamic-pituitary-ovarian axis and metabolic homeostasis." (PMID 41220482, 2025). "This study investigates serum anti-Müllerian hormone (AMH) and its correlation with insulin resistance and lipid profiles to identify predictive markers for PCOS risk in adolescents." (PMID 41220482, 2025). "Similar findings were confirmed by other studies, however, some studies reported higher levels of AMH in PCOS women with insulin resistance, compared with those with normal insulin sensitivity." (PMID 37034292, 2023). "It is described in the literature that high levels of AMH occur in PCOS patients who have insulin resistance." (PMID 38813505, 2023). "Phenotype A, within the Rotterdam criteria classification, exhibited the highest anti-Müllerian hormone levels (AMH), while phenotype D displayed the lowest Homeostasis Model Assessment of Insulin Resistance (HOMA-IR) values." (PMID 37568475, 2023). "The possible reason is that low AMH value is a phenotype of insulin resistance which is related to vascular damage, thus leading to an increased likelihood of HDP in DOR patients." (PMID 37061732, 2023). "Another hormone involved in the pathogenesis and insulin resistance in the pathophysiology of PCOS is the Anti-mullerian hormone (AMH)." (PMID 34627352, 2021). "It is important to investigate the possibility of using AMH as a marker of some parameters: improved insulin resistance and decreased LH and androgen levels." (PMID 27882049, 2016). "The positive correlation between insulin resistance and serum AMH levels suggests that insulin exerts an action on AMH synthesis; however this aspect is not yet fully understood." (PMID 27882049, 2016). "These correlations were successively confirmed, and a further relationship between AMH levels and insulin resistance indexes was demonstrated in untreated PCOS patients." (PMID 20663178, 2010). "The degree of AMH reduction varies among women, depending on baseline insulin resistance, severity of PCOS, and individual responsiveness to metformin.Personalizing metformin therapy by regularly measuring AMH levels ensures more targeted and effective management of PCOS and IR." (PMID 40281834, 2025). "The postoperative reversion of insulin resistance may impact granulosa cells function and consequently alter AMH concentration." (PMID 38559698, 2024).
Insulin resistance (continued). "In a post hoc analysis of our LIFEstyle RCT, we investigated if resumption of ovulation after a 6-month lifestyle intervention in women with PCOS and obesity was associated with changes in endocrine and metabolic parameters (weight, insulin resistance, AMH, and androgens)." (PMID 38503490, 2024). "Is resumption of ovulation after a 6-month lifestyle intervention in women with PCOS and obesity associated with differential changes in endocrine and metabolic parameters (weight, insulin resistance, anti-Müllerian hormone (AMH), and androgens) compared to women with PCOS who remained anovulatory?" (PMID 38503490, 2024). "Statistically very strong elevations of TRB3 and AMH in all PCOS groups may indicate a relationship between insulin resistance, impaired metabolic parameters, obesity and PCOS." (PMID 38813505, 2023). "Factors apt for further investigation include the extent to which PCOS phenotypes, BMI, obesity, insulin resistance, hyperandrogenemia, SHBG, hs-CRP, CTRP6, adiponectin, plasma leptin, homocysteine, AMH and thrombophilia contribute to further risk of miscarriage." (PMID 38027110, 2023). "AMH levels and indicators of insulin resistance are closely connected with DPP4, and DPP4 might be an additional characteristic of the metabolic imbalances associated with PCOS." (PMID 35909514, 2022). "The primary outcome would be anti-Mullerian hormone (AMH) level; the secondary outcomes would be biochemical profiles, ovarian volume, antral follicle count, BMI, menstrual frequency, and homeostasis model assessment of insulin resistance (HOMA-IR)." (PMID 35658926, 2022). "Recent research suggests that the diversity of AMH genotypes in the AMH signal pathway may be connected with the susceptibility and phenotype of PCOS with insulin resistance." (PMID 33763302, 2021). "Circulating levels of AMH are significantly higher in women with PCOS at all ages; AMH levels have been correlated with circulating androgens as well as with insulin resistance, and a role for AMH in PCOS pathogenesis is hypothesized." (PMID 34063169, 2021). "Interestingly enough, serum AMH levels showed positive correlation with insulin resistance, free androgen index, and LDL cholesterol levels, and negative correlation with HDL cholesterol levels." (PMID 25119192, 2014). "One interpretation of this result that seems plausible is that although insulin resistance does play a significant role in fertility, it may not be associated with ovarian reserve and thus AMH levels in particular." (PMID 39683543, 2024). "Moreover, brothers of women with PCOS have increased AMH hormone levels, altered gonadotrophin, and steroidogenic secretion, as well as a metabolic phenotype with insulin resistance and pancreatic β-cell dysfunction, dyslipidemia, and an increased cardiovascular disease risk." (PMID 37148878, 2023). "Thus, high AMH levels and insulin resistance might contribute to the pathogenesis of PCOS independently." (PMID 37381009, 2023). "The abnormal level of AMH increases the level of inflammatory factors, resulting in a continuous low concentration of systemic inflammatory state in the human body, leading to metabolic diseases such as insulin resistance and glycolipid metabolism and reproduction disfunction." (PMID 32785222, 2020). "Owing to its cross-sectional design, a causative relationship between AMH and insulin resistance could not be explored." (PMID 29426356, 2018). "Another cross-sectional analysis of 252 women aged 18–46 with PCOS revealed that AMH levels correlated positively with HDL-C cholesterol and negatively with fasting glucose, insulin resistance, BMI, SBP, and DBP." (PMID 38926704, 2024). "Fasting blood sugar (FBS), insulin resistance (IR), total antioxidant capacity (TAC), malondialdehyde (MDA), C-reactive protein (CRP), tumor necrosis factor-alpha (TNF-α), and AMH were measured before and after the study." (PMID 38778429, 2024).